HIF1A (hypoxia inducible factor 1 subunit alpha)
Diseases named in the same sentence as HIF1A in open-access papers (continued):
Sharing a sentence is not in itself a finding about the gene and the disease.
lymph node metastasis (continued). "Further clinically relevant analysis showed that elevated HIF-1α and NRP1 expression was associated with lymph node metastasis." (PMID 33850110, 2021). "Multivariate Cox regression analysis identified lymph node metastasis and nuclear HIF-1A expression to be independent prognostic parameter in GBC." (PMID 33403040, 2021). "We found lymph node metastasis [p = 0.032, HR (hazard ratio) = 2.435, 95% CI: 1.078-5.502] and nuclear HIF-1A expression [p =0.002, HR (hazard ratio) = 2.129, 95% CI: 1.308-3.466] as independent prognostic factors for OS in GBC patients." (PMID 33403040, 2021). "We further explored the association between clinicopathological features and the expression of PD-L1 and HIF-1α protein, which mainly contained histological type, pathological grade, lymph node metastasis (LNM) status, age, gender and clinical stage." (PMID 33754005, 2021). "In multivariate analysis, lymph node metastases (HR 2.03, p = 0.0186) in primary tumors and grade B.C (HR 2.21, p = 0.0057) and high HIF-1α expression (HR 2.40, p = 0.0079) in metastatic tumors were independent recurrent factors." (PMID 32895059, 2020). "HIF-1α is considered to be a potential prognostic marker of many cancers, including OSCC17, and HIF-1α overexpression has been correlated with tumor stage, lymph node metastasis, and poor survival in OSCC18." (PMID 32883954, 2020). "As the independent recurrent factor, lymph node metastases in primary factors and synchronous, grade B.C, and high HIF-1α expression in metastatic tumors were observed." (PMID 32895059, 2020). "Univariate analyses showed that T classification (P = 0.034), lymph node metastases (P < 0.01), clinical stage (P < 0.01), HIF-1α expression (P < 0.01) and MMP-13 expression (P < 0.01) were all significantly correlated with patients’ survival." (PMID 29515112, 2018). "The frequency of distribution of HIF1A SNP CC genotype is significantly correlated with tumor size and lymph node metastasis." (PMID 26872370, 2016). "HIF-1α is associated with the malignantdegree, FIGO stage, histological grade, lymph node metastasis, 5-years survival rate and recurrence rate of gynecological cancer." (PMID 25993275, 2015). "We performed pooled analyses with available data on the association between HIF-1α expression and pathological type, FIGO stage, histological type, and lymph node metastasis." (PMID 25993275, 2015). "Higher levels of HIF-1α expression in this study correlated strongly with lymph node metastasis, which indicates that HIF-1α is involved in tongue cancer metastasis." (PMID 23599780, 2013). "In multivariate analysis, lymph node metastases, age and HIF-1α expression retained independent prognostic significance." (PMID 24165149, 2013). "HIF-1α overexpression correlated with clinical stage and lymph node metastasis in patients with carcinoma of the tongue." (PMID 23599780, 2013). "Increased expression of HIF-1α correlated significantly with clinical stage (P=0.002) and lymph node metastasis (P=0.034)." (PMID 23599780, 2013). "HIF-1α and MDR1/P-gp expression was high in the LSCC tissues and was associated with the clinical stage and lymph node metastasis (P<0.05)." (PMID 23946810, 2013). "The correlation between HIF-1α expression and lymph node metastasis or clinical stage was indicated by Spearman correlative analysis (P= 0.034 and P=0.002, respectively)." (PMID 23599780, 2013). "Of the tumor-related factors, it suggested that increased vascular invasion, tumor grade and lymph node metastasis were correlated with HIF-1α according to the 7 selected studies." (PMID 23799043, 2013). "Univariate analyses identified high HIF-1α positivity, depth of tumour invasion, lymph node metastasis, distant metastasis, lymphatic invasion, and a positive surgical margin as risk factors." (PMID 12966423, 2003).
lymph node metastasis (continued). "High HIF-1α expression correlated with pTNM stage, depth of tumour invasion, lymph node metastasis, distant metastasis, lymphatic invasion and positive surgical margin." (PMID 12966423, 2003). "We have demonstrated that patients with high HIF1A expression are more likely to develop lymph node metastases, which may explain the unfavorable prognosis in the high HIF1A expression group." (PMID 36994412, 2023). "Furthermore, HIF-1α was also shown to strongly correlate with a higher rate of lymph node metastasis and vasculogenic mimicry." (PMID 35163556, 2022). "HIF-1α potential as a marker to identify patients with lymph node metastasis was investigated." (PMID 34298636, 2021). "For PFS a significant association was found for heritability, stage, lymph node metastases, disease status, necrosis, HIF-1α and Glut-1, but not for SSTR2A expression." (PMID 30128959, 2018). "On the other hand, high HIF-1α expression in the tumor stroma was significantly more frequent in patients with non-endometrioid tumor subtype, high grade tumors, lymph node metastasis, high FIGO stage and in tumors with loss of hormone receptors." (PMID 27634881, 2016). "Using Kaplan-Meier univariate analysis, six factors were found to have statistically significant associations with the OS time of patients with GAC following curative surgery, including STAT3, p-STAT3, HIF-1α, VM, status of lymph node metastasis and degree of differentiation (P<0.05)." (PMID 24959290, 2014). "Furthermore, we also found that the expression of HIF-1α was correlated with lymph node metastasis, TNM stage and poorly differentiated histological grade (P < 0.05)." (PMID 23445622, 2013). "More importantly, the expression of HIF-1α correlated closely with lymph node metastasis and could be a reliable marker to predict the prognosis of tongue cancer." (PMID 23599780, 2013). "Additionally, a significant correlation was found between lymph node metastasis and the expression of HIF-1α (P = 0.029) or Foxp3 (P<0.001)." (PMID 23723999, 2013). "Moreover, our data also indicate that the combined high expression of HIF-1α, CXCR4, and VEGF is significantly associated with lymph node metastasis and distant metastasis." (PMID 20953377, 2010). "Statistical analysis indicated that combined high expression of both HIF-1α and VEGF is significantly associated with lymph node metastasis as compared with that of a single molecule's high expression alone (P = .007) and cases without distant metastasis (P = .067)." (PMID 20953377, 2010). "A previous meta-analysis comprising nine studies on HIF1A and clinicopathological features in GC10 reported that positive HIF1A protein level was associated with TNM stage progression, differentiated GC cell status, T stage progression, vascular invasion, and lymph node metastasis." (PMID 38877062, 2024). "Finally, another meta-analysis based on 30 NSCLC studies reported that HIF-1α expression was higher in the presence of lymph node metastasis (OR = 3.72; p < 0.0001), poor degrees of differentiation (OR = 2.12; p < 0.0001), or SqCC histology in comparison to AC (OR = 1.28; p = 0.03)." (PMID 34298636, 2021). "For example, the expression levels of HIF-1α were assessed in a cohort of 66 NSCLC who underwent surgical resection, where high HIF-1α expression was associated with poor outcomes, but exclusively in node-negative patients and not in patients with lymph node metastasis." (PMID 34298636, 2021). "Additionally, chi-square test showed a significant association between the presence of lymph node metastasis with HIF-1α (P = 0.006) and HIF-2α expression (P = 0.037).There was also a statistical significance between capsular invasion with the expression of HIF-1α (P = 0.012) and HIF-2α (P = 0.004)." (PMID 26846782, 2016). "Clinically, high expression of HIF-1α and TGF-β1 correlates significantly with advanced TNM stages and lymph node metastasis, suggesting their potential as biomarkers for fibrosis and invasiveness." (PMID 40406267, 2025).
lymph node metastasis (continued). "The expression of HIF-1α was related to the histological grade and lymph node metastasis in TNBC, and the expression of CD147 was related to Ki-67, histological grade and lymph node metastasis." (PMID 38847725, 2024). "In particular, the inhibition of the lncRNA HIF1A-AS1 increases apoptosis by reducing HIF-1α/mTOR-induced autophagy, while its overexpression is related to the TNM stage and lymph node metastasis." (PMID 37189787, 2023). "Phenotype abnormality of this axis (HIF-1α+/PKM2+) was significantly correlated with bigger tumor size (76.1% vs 28.6%), capsular invasion (78.0% vs 36.8%) and lymph node metastasis (82.4% vs 42.3%) (P < .05)." (PMID 36897686, 2023). "A logistic regression analysis showed that tumor size, lymph node metastasis, incomplete enhancement and iso-enhancement of PED were independent predictors for HIF-1α-high PDACs and GLUT1-high PDACs." (PMID 37892091, 2023). "Analysis results showed that the expression of HIF-1α in CNC was only correlated with histological grade (p < 0.05), and it was related to lymph node metastasis, clinical stage, and pathologic stage in BLBC (p < 0.05)." (PMID 37114130, 2023). "In univariate analysis, we found that histological differentiation grade (p = 0.003), depth of invasion (p = 0.016), lymph node metastasis (p = 0.002), TNM stages (p = 0.011), nuclear HIF-1A expression (p< 0.001) were statistically significant factors for OS." (PMID 33403040, 2021). "Although we were unable to find studies connecting HIF-1α expression with POI, the relationship we revealed may show an indirect association between HIF-1α expression and lymph node metastasis as POI type IV is significantly associated with lymph node metastasis." (PMID 33123565, 2020). "Multivariate analysis showed that grade of differentiation, lymph node metastasis CHCHD2 and HIF-1α expressions were all showed significantly higher hazard ratios, which indicated that these factors would been independent prognostic factors of NSCLC." (PMID 32054470, 2020). "Our data confirmed their findings, since a significant correlation was found between HIF-1α expression and TNM-stage, lymph node metastasis and grade of desmoplasia." (PMID 28404916, 2017). "Among these markers, expression of HIF-1α and c-Met were significantly different in FIGO stage (P < 0.001 and P = 0.019, respectively) and patients with lymph node metastasis (P < 0.001 and P = 0.010, respectively)." (PMID 23927384, 2013). "In lymph node metastases, 21.7, 66.7 and 26.7% were positive for, respectively, CA9, DEC-1 and Hif-1α." (PMID 16251878, 2005). "The survival rate for patients with HIF-1α positive staining has been reported as significantly lower than that for patients with HIF-1α negative staining, due to higher rates of lymph node metastases and venous invasion." (PMID 40142263, 2025). "We come to the conclusion that the presence of a high HIF-1α level indicates an unfavorable prognosis in patients with lymph node-negative disease but not in those with lymph node metastasis, which is consistent with the previous study." (PMID 38609977, 2024). "Both HIF-1α-high PDACs and GLUT1-high PDACs had a larger tumor size (3.68 ± 1.76 vs. 3.07 ± 1.03 p = 0.002; 3.80 ± 1.70 vs. 2.90 ± 1.10 p = 0.002, respectively) and were more prone to lymph node metastasis (p = 0.009 and p = 0.026, respectively)." (PMID 37892091, 2023). "A high HIF-1α expression was correlated with lymph node metastasis but not with survival, in glioma, nasopharyngeal cancer, and renal cancer." (PMID 35890106, 2022). "The positive expression rate of HIF-1α in poorly differentiated group and lymph node metastasis group exceeds than that in highly differentiated and nonmetastasis groups, but the difference was not statistically significant (p > 0.05)." (PMID 35664561, 2022).
lymph node metastasis (continued). "The positive expression rate of HIF-1α in low differentiation group and lymph node metastasis group was higher than that in high differentiation group and no lymph node metastasis group." (PMID 35664561, 2022). "HIF-1α-positivity correlated to negative prognostic factors including low age at diagnosis, presence of lymph node metastasis, high tumor stage, ERα- and PR-negativity, overexpression of HER2, and high Ki67-expression." (PMID 31821370, 2019). "Contrarily, the NEDD4L and HIF-1α expression did not correlate with gender, age, lymph node metastasis and tumor location." (PMID 31673244, 2019). "The expression of HIF-1α in III‒IV stage or lymph node metastasis was significantly higher than that in I‒II stage or that without lymph node metastasis, respectively (OR=2.66, 95% (CI): 1.87,3.79, p<0.00001; OR= 3.98, 95% (CI): 2.10,12.89, p<0.0001)." (PMID 25993275, 2015). "A significant difference in the levels of HIF-1α expression was detected between groups of patients with lymph node metastases and patients with no metastases." (PMID 23599780, 2013). "VM and the expressions of CD82/KAI1 and HIF-1α in NSCLC are related to differentiation, lymph node metastasis, clinical staging, and prognosis.The combined detection of CD82/KAI1, HIF-1α, and VM has an important role in predicting the progression and prognosis of NSCLC." (PMID 22152691, 2011). "We found a significant correlation between HIF-1α and leptin expression in primary tumors and lymph node metastases in patients who did not receive preoperative chemotherapy." (PMID 20569445, 2010). "Results demonstrated that mean HIF-1α mRNA expression levels were 1.05 ± 0.58-fold in negative control group, 1.19 ± 0.52-fold in lymph node metastasis group, and 1.09 ± 0.32-fold in distant metastasis group." (PMID 20953377, 2010). "On the other hand, a positive correlation between HIF-1α and Glut-1 was found in primary tumors, but not in lymph node metastasis in patients without preoperative chemotherapy." (PMID 20569445, 2010). "In lymph node metastases from women without neoadjuvant therapy, a trend toward a positive correlation between HIF-1α and ObR was detected." (PMID 20569445, 2010). "A strong correlation was found for Hif-1α (P<0.001): in only one case one lymph node metastasis expressed Hif-1α, while the other did not." (PMID 16251878, 2005). "Multivariate analyses indicated that depth of tumour invasion, lymph node metastasis and positive surgical margin, but not HIF-1α, were independent prognostic factors." (PMID 12966423, 2003). "Furthermore, tissues with lymph node metastasis showed higher HIF-1α expression than tissues without lymph node metastasis." (PMID 39858431, 2024). "The results of the present meta-analysis showed that increased expression of HIF-1α protein, as detected with IHC, was significantly associated with larger tumor size (T3/T4), more advanced TNM stage (III/IV), and lymph node metastasis, but not with poor differentiation." (PMID 28521842, 2017). "Moreover, lymph node metastasis is not a result of high expression of HIF-1α or CAIX in CK-160 and TS-415 tumors." (PMID 26502718, 2015). "Furthermore, the expression of HIF-1α was significantly different between groups of patients with lymph node metastasis and no metastasis (P<0.05)." (PMID 23599780, 2013). "Notably, STAT3-, p-STAT3- and HIF-1α-positive expression and VM formation in tissues from patients with lymph node metastasis were significantly higher than those from patients without lymph node metastasis, respectively (92.7 vs. 57.9, 75.6 vs. 21.1, 78.0 vs. 31.6 and 41.5 vs. 10.5%; P<0.05)." (PMID 24959290, 2014). "Correlation between HIF-1α, GLUT-1 and other studied biomarkers in lymph node metastases in patients without and after preoperative chemotherapy." (PMID 20569445, 2010). "The expression of survivin or HIF-1α in NSCLC was not correlated with age or sex, but with differentiation grade, lymph node metastasis and disease stages." (PMID 19245702, 2009).
Insulin resistance (85 papers, 2009 to 2026). Increased resistance towards insulin, that is, diminished effectiveness of insulin in reducing blood glucose levels. "Hypoxia-induced HIF-1α accumulation in adipocytes is implicated in chronic inflammation, tissue fibrosis, adipose dysfunction and insulin resistance." (PMID 32752112, 2020). "The activation of adipocyte HIF1α results in adipose tissue inflammation, fibrosis, and systemic insulin resistance, whereas its loss of function exhibits opposite phenotypes." (PMID 32408016, 2020). "Reportedly, Hif1a deficient mice under a high-fat diet exhibited beneficial effects in adipose tissue inflammation and insulin resistance development." (PMID 30619282, 2018). "HIF-1α is a master regulator of oxygen homeostasis, and activation of HIF-1α is associated with the sympathetic response, increased triglyceride levels and insulin resistance, linking the hypoxic and proinflammatory response pathways." (PMID 25654228, 2015). "Targeting key nodes within this network—such as the IL-17 receptor, TLR4, or HIF-1α—may offer a multidimensional therapeutic strategy for insulin resistance (IR) and its associated complications." (PMID 40625623, 2025). "Insulin resistance (IR) is a villain role to the pathology of fatty liver diseases implicated in adipose tissue dysfunction, which is characterized by lipid droplets (LDs) accumulation and hypoxia-inducible factor 1α (HIF1α) related macrophage infiltration." (PMID 34889901, 2021). "Notably, our findings differ from a recent report that myeloid deficiency of HIF-1α improved systemic insulin resistance, as well as WAT inflammation, in a similar model of diet-induced obesity." (PMID 32221369, 2020). "Alternatively, another obesity-related factor that may regulate REDD1 expression is the hypoxia-regulated transcription factor HIF1α, which has also been implicated in the development of insulin resistance." (PMID 27613400, 2016). "Overall, our results suggest that VAT HIF-1α mRNA expression could be associated with the pathogenesis of insulin resistance." (PMID 26619907, 2015). "In addition to causing insulin resistance, oxidative stress could induce HIF-1α and HIF-2α, as shown by the preferential increase in the mRNA levels of these transcription factors in the NMN + OLE group." (PMID 34948019, 2021). "Since in previous studies we have demonstrated that insulin resistance was associated with the expression of genes involved in lipid metabolism and with other proteins in adipose tissue, we wanted to determine whether insulin resistance is also associated with HIF-1α." (PMID 26619907, 2015). "First, HIF-1α depletion attenuated diet-induced hepatic steatosis; hepatic lipotoxicity has been implicated in the development of hepatic insulin resistance, and therefore treatment of lipotoxicity may improve insulin resistance." (PMID 23049707, 2012). "HIF-1α-positive Treg cells correlated positively with adiposity and insulin resistance markers; however, after False Discovery Rate (FDR) correction, correlations no longer remained statistically significant." (PMID 41977296, 2026). "Lipidomic analysis revealed a decrease in diacylglycerols (DGs) and ceramides, implicating pathways such as sphingolipid and phosphatidylinositol metabolism, in addition to HIF-1α signaling, insulin resistance, and diabetic complications." (PMID 41554705, 2026). "Cell culture studies indicate that HIF-1α regulates both glucose uptake and glycolytic enzyme activity, significantly enhancing the glycolysis process as a mediator of insulin resistance." (PMID 41155523, 2025). "TNF can activate STAT3, HIF-1a, Th17, and IL-6, while IL-1 can induce insulin resistance, HIF-1 production, and JAK-STAT signals." (PMID 39891057, 2025). "This state of hypoxia elicits a myriad of transcriptional factors, such as hypoxia-inducible factor 1 alpha (HIF1α), that can prompt an inflammatory response and lead to metabolic syndromes, including insulin resistance." (PMID 39566173, 2024).